KICS2 (KICSTOR subunit 2)
Description:
As part of the KICSTOR complex functions in the amino acid-sensing branch of the TORC1 signaling pathway. Recruits, in an amino acid-independent manner, the GATOR1 complex to the lysosomal membranes and allows its interaction with GATOR2 and the RAG GTPases. Functions upstream of the RAG GTPases and is required to negatively regulate mTORC1 signaling in absence of amino acids. In absence of the KICSTOR complex mTORC1 is constitutively localized to the lysosome and activated. The KICSTOR complex is also probably involved in the regulation of mTORC1 by glucose.
Synonyms: C12orf66; FLJ32549; MRT83
Tractability: PROTAC: ubiquitination databases record sites on it.
Gene: Protein-coding gene on chromosome 12 (64,186,226 to 64,222,296, reverse strand). Ensembl gene ENSG00000174206.
Subcellular location: Lysosome membrane
Subcellular location (Human Protein Atlas): Lysosomes; Cytokinetic bridge
Pathways (Reactome):
Cellular responses to stimuli: Amino acids regulate mTORC1
Gene Ontology:
Biological process: cellular response to amino acid starvation; cellular response to glucose starvation; negative regulation of TORC1 signaling; protein localization to lysosome; regulation of TORC1 signaling
Cellular component: KICSTOR complex; lysosomal membrane
Genetic constraint (gnomAD): Loss-of-function variants: 13 observed, 33.38 expected, observed/expected ratio (o/e) 0.39, 90% interval 0.25 to 0.62. The upper end of that interval is the gene's LOEUF score, 0.62, which puts it in group 2 of 6, group 1 being the genes least tolerant of losing a copy. Missense variants: 455 observed, 574.42 expected, observed/expected ratio (o/e) 0.79, 90% interval 0.73 to 0.86. Synonymous variants: 209 observed, 230.06 expected, observed/expected ratio (o/e) 0.91, 90% interval 0.81 to 1.02.
Homologues: Orthologues: chimpanzee KICS2 (99% identical), macaque KICS2 (99% identical), guinea pig KICS2 (98% identical), rabbit KICS2 (97% identical), dog KICS2 (97% identical), mouse Kics2 (95% identical), rat Kics2 (95% identical), pig KICS2 (86% identical), tropical clawed frog kics2 (82% identical), zebrafish kics2 (75% identical).
Diseases named in the same sentence as KICS2 in open-access papers:
KICS2 is named in the same sentence as 7 diseases in open-access papers, as found by Europe PMC text mining. Sharing a sentence is not in itself a finding about the gene and the disease. The quoted sentences say what the papers report.
Intellectual disability (1 paper, 2025). "A recent study demonstrated that mutations in KICSTOR subunit 2 (KICS2) affect the KICSTOR (KPTN, ITFG2, C12orf66, and SZT2 regulatory) complex, which negatively regulates mTORC1 signaling, resulting in intellectual disability." (PMID 41236931, 2025).
viral infection (1 paper, 2025). "Specifically, KICS2 has been shown to interact with influenza A virus proteins as well as hepatitis C virus proteins to promote viral infection." (PMID 39880866, 2025).
KICS2 also shares sentences with these, for which no sentence is quoted: autosomal recessive intellectual disability (1 paper); cancer (1); colorectal cancer (1); epilepsy (1); neuroblastoma (1).